PRKCSH (PRKCSH beta subunit of glucosidase II)
Description:
Regulatory subunit of glucosidase II that cleaves sequentially the 2 innermost alpha-1,3-linked glucose residues from the Glc(2)Man(9)GlcNAc(2) oligosaccharide precursor of immature glycoproteins. Required for efficient PKD1/Polycystin-1 biogenesis and trafficking to the plasma membrane of the primary cilia (By similarity).
Synonyms: PKCSH; G19P1; VASAP-60; GIIB; 80K-H; AGE-R2; GIIbeta; GluIIbeta; PCLD; PCLD1; PLD1
Tractability: Antibody: UniProt predicts a signal peptide or a membrane-spanning region. PROTAC: ubiquitination databases record sites on it; its protein half-life has been measured.
Target class: Enzyme
Gene: Protein-coding gene on chromosome 19 (11,422,369 to 11,450,969, forward strand). Ensembl gene ENSG00000130175.
Subcellular location: Endoplasmic reticulum
Subcellular location (Human Protein Atlas): Endoplasmic reticulum
Pathways (Reactome):
Metabolism of proteins: Calnexin/calreticulin cycle; N-glycan trimming in the ER and Calnexin/Calreticulin cycle; Post-translational protein phosphorylation; Regulation of Insulin-like Growth Factor (IGF) transport and uptake by Insulin-like Growth Factor Binding Proteins (IGFBPs)
Cell-Cell communication: Regulation of CDH1 posttranslational processing and trafficking to plasma membrane
Disease: Maturation of spike protein
Immune System: Advanced glycosylation endproduct receptor signaling
Gene Ontology:
Molecular function: phosphoprotein binding; protein binding; protein kinase C binding; transmembrane transporter binding; calcium ion binding
Biological process: N-glycan processing; intracellular signal transduction; liver development
Cellular component: endoplasmic reticulum; glucosidase II complex; intracellular membrane-bounded organelle; endoplasmic reticulum lumen
Genetic constraint (gnomAD): Loss-of-function variants: 41 observed, 76.14 expected, observed/expected ratio (o/e) 0.54, 90% interval 0.42 to 0.7. The upper end of that interval is the gene's LOEUF score, 0.7, which puts it in group 2 of 6, group 1 being the genes least tolerant of losing a copy. Missense variants: 681 observed, 709.98 expected, observed/expected ratio (o/e) 0.96, 90% interval 0.9 to 1.02. Synonymous variants: 324 observed, 283.54 expected, observed/expected ratio (o/e) 1.14, 90% interval 1.04 to 1.25.
Gene-disease validity (ClinGen):
ClinGen rates the evidence that PRKCSH causes each of these diseases.
polycystic liver disease 1 (autosomal dominant): Definitive.
Homologues: Orthologues: chimpanzee PRKCSH (99% identical), macaque PRKCSH (96% identical), pig PRKCSH (89% identical), dog PRKCSH (89% identical), guinea pig PRKCSH (87% identical), mouse Prkcsh (86% identical), rat Prkcsh (85% identical), zebrafish prkcsh (59% identical), tropical clawed frog prkcsh (57% identical), Caenorhabditis elegans ZK1307.8 (34% identical), Drosophila melanogaster CG7685 (11% identical). Paralogues in human: GNPTG (11% identical).
Diseases named in the same sentence as PRKCSH in open-access papers:
PRKCSH is named in the same sentence as 55 diseases in open-access papers, as found by Europe PMC text mining. Sharing a sentence is not in itself a finding about the gene and the disease. The quoted sentences say what the papers report.
lung carcinoma (10 papers, 2016 to 2026). "Bioinformatics analysis of PRKCSH expression in cancer databases to study its role in lung cancer revealed that higher PRKCSH expression was linked to worse outcomes for lung cancer patients." (PMID 38571496, 2024). "To clarify the function of GluIIβ in lung cancer cells, we knockout PRKCSH, the GluIIβ encoding gene, in A549 and H1299 non-small cell lung cancer cells." (PMID 31316108, 2019). "PRKCSH has been associated with protection from apoptosis and promoting self-renewal in lung cancer cell line." (PMID 27768780, 2016). "PRKCSH encodes the beta-subunit of glucosidase II and has been shown to be associated with inhibition of apoptosis and induction of cell proliferation of lung cancer cells." (PMID 27768780, 2016). "PRKCSH expression level was negatively associated with STAT6 levels in lung cancer tissues." (PMID 38571496, 2024). "Thus, we investigated whether the PRKCSH-mediated extension of the IGF1R half-life is linked to IRE1α activation in lung cancer." (PMID 38200153, 2024). "Caspase-8 phosphorylation was significantly increased by TRAIL treatment in lung cancer cells; however, it was almost completely inhibited by PRKCSH depletion." (PMID 38200153, 2024). "The overexpression of Mcl-1L in PRKCSH-deficient cells suppressed TRAIL-mediated cell death and caspase-9 activation, whereas Mcl-1 depletion in lung cancer cells enhanced TRAIL-mediated cell death and caspase-9 activation." (PMID 38200153, 2024). "To investigate PRKCSH-related functional events, we searched the TCGA database of lung cancer to identify genes correlated with PRKCSH mRNA expression." (PMID 38200153, 2024). "PRKCSH (protein kinase C substrate 80K-H) was also selected by sCCA for the lung dataset, and this gene was shown to be significantly up-regulated in lung cancer tissues." (PMID 38790260, 2024). "Here, we demonstrate that protein kinase C substrate 80K-H (PRKCSH) abundance in lung cancers boosts oncogenic IGF1R activation, leading to TNFSF resistance." (PMID 38200153, 2024). "In the present study, IGF1R expression was found to be upregulated in lung cancer patient tissues, and its protein levels were correlated with PRKCSH protein levels." (PMID 38200153, 2024). "We also reported that knockout of PRKCSH gene inhibited growth and metastatic potential of lung cancer cells by inhibiting receptor tyrosine kinase activities." (PMID 38571496, 2024). "The findings revealed that primary breast cancer, colon cancer, ovarian cancer, clear cell RCC, UCEC, lung cancer, head and neck squamous carcinoma, and glioblastoma exhibited higher levels of the total PRKCSH protein." (PMID 38245572, 2024). "Researchers at Sungkyunkwan University in South Korea have discovered that a protein named PRKCSH is vital in assisting lung cancer cells to resist TNFs." (PMID 38200153, 2024). "Our data also showed that PRKCSH depletion promoted the degradation of the autolysosomal substrate SQSTM1 protein in lung cancer cells, and its level was increased via the lysosome inhibitor CQ." (PMID 38200153, 2024). "To first investigate the expression levels of PRKCSH in lung cancer, we analyzed PRKCSH mRNA expression using datasets from The Cancer Genome Atlas (TCGA) database." (PMID 38200153, 2024). "The expression of the PRKCSH gene was significantly upregulated in liver, colon, gastric, breast, and lung cancer tissues." (PMID 31320625, 2019). "In lung cancer, PRKCSH controls cell adhesion molecules (CAMs), which are essential for T-cell surveillance,], stabilizes the insulin-like growth factor 1 receptor (IGF1R), and increases resistance to tumor necrosis factor superfamily (TNFSF)-induced apoptosis." (PMID 41350724, 2025). "In addition, knocking out PRKCSH has been shown to inhibit the growth and migration of lung cancer cells by disrupting receptor tyrosine kinase activities." (PMID 38245572, 2024).
lung carcinoma (continued). "The gain of IGF1R in PRKCSH-deficient cells increased caspase-8 phosphorylation and Mcl-1 expression levels, whereas IGF1R knockdown reduced caspase-8 phosphorylation and Mcl-1 expression levels in lung cancer cells." (PMID 38200153, 2024). "Subsequently, we analyzed PRKCSH mRNA expression levels at different stages of lung cancer." (PMID 38200153, 2024). "Indeed, Mcl-1 expression in PRKCSH-deficient cells reversed TRAIL resistance, whereas Mcl-1 knockdown increased TRAIL sensitivity in lung cancer cells." (PMID 38200153, 2024). "PRKCSH abundance is correlated with IGF1R upregulation in lung cancer tissues." (PMID 38200153, 2024). "Increased PRKCSH protein expression was observed in breast cancers and lung cancer." (PMID 38571496, 2024). "Importantly, a follow-up analysis of patient survival using Kaplan‒Meier curves revealed that high expression of PRKCSH mRNA was correlated with poor first-progression survival and overall survival in patients with lung cancer." (PMID 38200153, 2024). "Therefore, targeting PRKCSH may be a promising therapeutic strategy for various tumors including IGF1R-related lung cancer." (PMID 38200153, 2024). "Alternative splicing generates distinct PRKCSH isoforms, which can influence processes like epithelial-mesenchymal transition (EMT) and the proliferation of lung cancer cells." (PMID 38571496, 2024). "PRKCSH depletion also inhibited ER stress-induced IRE1α activation and XBP-1 splicing in lung cancer cells." (PMID 38200153, 2024). "recently showed that PRKCSH increased the stability and activation of the insulin-like growth factor 1 receptor (IGF1R) in lung cancer." (PMID 38571496, 2024). "PRKCSH depletion promoted the interaction between HERPUD1 and IGF1R in lung cancer cells." (PMID 38200153, 2024). "However, the potential role of PRKCSH in the development and progression of lung cancer has not yet been elucidated." (PMID 38200153, 2024). "Indeed, PRKCSH mRNA levels are not correlated with IGF1R mRNA levels in lung cancer." (PMID 38200153, 2024).
polycystic liver disease (9 papers, 2015 to 2025). "Mutations in protein kinase C substrate 80K-H (PRKCSH), which encodes for an 80 KDa protein named hepatocystin (80K-H, PRKCSH), gives rise to polycystic liver disease (PCLD)." (PMID 26671672, 2015). "The remaining case (a positive finding in PRKCSH) was reclassified from a polycystic kidney disease to polycystic liver disease, which substantially altered the patient's prognosis." (PMID 37794564, 2023). "Mutations in PRKCSH and GANAB, human orthologs of GTB1 and ROT2, are linked to polycystic liver disease." (PMID 32994210, 2020). "Family history was not known, but she carried a non-sense mutation p.(Tyr423*) in PRKCSH, a gene associated to polycystic liver disease-1 (PCLD1) with or without kidney cysts." (PMID 32457805, 2020). "Of note, 4 patients in the COL4A3 cohort had liver cysts and despite no potentially pathogenic variants being found in genes associated with polycystic liver disease (PRKCSH, SEC63, and LRP5), we cannot completely rule out the presence of a second variant contributing to this phenotype." (PMID 39190485, 2024). "PRKCSH has various aliases including 80K-H, hepatocystin, PCLD (polycystic liver disease), PLD1 (phospholipase D1, phosphatidylcholine-specific), G19P1, advanced glycation end product receptor-2 (AGE-R2), and Protein kinase C substrate 60.1 kDa protein heavy chain." (PMID 38571496, 2024).
autosomal dominant polycystic liver disease (8 papers, 2015 to 2024). An autosomal dominant inherited condition characterized by many cysts of various sizes scattered throughout the liver. "Mutations in the PRKCSH gene have been identified in association with autosomal dominant polycystic liver disease (ADPLD)." (PMID 38571496, 2024). "Mutations in PRKCSH lead to Autosomal Dominant Polycystic Liver Disease (ADPLD), a rare hereditary disorder characterized by slowly progressive cyst formations." (PMID 26671672, 2015). "Mutations in the PRKCSH gene are linked to autosomal dominant polycystic liver disease (ADPLD)." (PMID 38571496, 2024). "Mutations in the PRKCSH gene have been associated with the inheritance pattern of autosomal dominant polycystic liver disease (ADPLD), and numerous alternatively spliced transcript variants have been documented, resulting in the production of different isoforms of PRKCSH." (PMID 38571496, 2024). "Autosomal Dominant Polycystic Liver Disease (ADPLD) leads to PLD only and is caused by a mutation in PRKCSH, SEC63, LRP5, ALG8 or SEC61B." (PMID 35216547, 2022).
cyst (6 papers, 2012 to 2023). A sac-like closed membranous structure that may be empty or contain fluid or amorphous material. "These mutations lead to total loss of functional PRKCSH in the cyst epithelium suggesting that PCLD is recessive on a cellular level." (PMID 23209713, 2012). "The germline mutation serves as the “first hit” and the somatic as the “second hit,” resulting in the loss of heterozygosity (LOH) of PRKCSH, which might be the reason for cyst formation." (PMID 35571028, 2022). "We therefore hypothesise that, similar to the situation in PRKCSH, somatic second-hit mutations are also an important step in cyst formation in patients with a SEC63 germline mutation." (PMID 23209713, 2012). "In conclusion, we have now shown that in both PRKCSH and SEC63 somatic second-hit mutations can occur which supports the notion that somatic second-hit mutations are part of the genetic mechanism in cyst formation in PCLD." (PMID 23209713, 2012). "ALG9 expression was absent in cyst wall lining from ALG9- and PRKCSH-caused ADPLD patients but present in the liver cyst lining derived from an ADPKD patient with a PKD2 variant." (PMID 37761895, 2023).
breast carcinoma (4 papers, 2019 to 2024). "Full-length PRKCSH has been shown to localize in the endoplasmic reticulum, whereas a truncated form in breast cancer cells could be seen associated with the nucleus, and even the plasma membrane, and intracellular vesicles." (PMID 37947649, 2023). "Note that we did not evaluate the impact of GPER1 overexpression on the localization of PRKCSH, but it has been reported for breast cancer cells that PRKCSH can translocate to the nucleus in a complex with the fibroblast growth factor 1 and its receptor FGFR." (PMID 37947649, 2023). "Some investigators have reported that PRKCSH is localized in the nucleus in breast cancer models." (PMID 31320625, 2019).
Kidney Cyst (3 papers, 2020 to 2024). Abnormal fluid filled sac within the kidney, either acquired or congenital. "PKD1 and PKD2 variants are linked to ADPKD regardless of the presence or absence of PLD, while PRKCSH and SEC63 variants are always associated with ADPLD without kidney cysts." (PMID 37761895, 2023).
liver cancer (3 papers, 2019 to 2024). An epithelial or non-epithelial malignant neoplasm that arises from the liver. "Immunohistochemical (IHC) analysis of an liver cancer tissue microarray also revealed that the incidence of PRKCSH positivity was higher in tumor tissues (positive samples: 45 out of 58; 77.6%) than in nontumor tissues (positive samples: 10 out of 59; 16.9%)." (PMID 31320625, 2019). "The inconsistent levels of mRNA and protein expression in patients with PAAD and liver cancer may stem from an unidentified post-transcriptional regulatory mechanism that hinders the translation of PRKCSH mRNA." (PMID 38245572, 2024). "Our previous study demonstrated that PRKCSH promotes IRE1α activity in liver cancer cells." (PMID 38200153, 2024). "However, surprisingly, PAAD and liver cancer presented a lower level of PRKCSH protein expression." (PMID 38245572, 2024).
lung adenocarcinoma (3 papers, 2024 to 2026). A carcinoma that arises from the lung and is characterized by the presence of malignant glandular epithelial cells. "In lung adenocarcinoma, high levels of PRKCSH expression have been linked to a poor prognosis, immune suppression, and resistance to cell death caused by stress." (PMID 41350724, 2025). "In conclusion, this study shows that PRKCSH coordinates cytokine regulation, immune cell reprogramming, and ER stress signaling to control tumor–immune dynamics in lung adenocarcinoma." (PMID 41350724, 2025). "According to this study, PRKCSH plays a significant role in tumor progression and immune modulation regulation of lung adenocarcinoma." (PMID 41350724, 2025). "PRKCSH mRNA levels were higher in lung adenocarcinoma (LUAD) and lung squamous cell carcinoma (LUSC) tissues than in normal tissues." (PMID 38200153, 2024). "In this study, we investigated whether PRKCSH affects the immune system and the stress responses of the endoplasmic reticulum (ER) in lung adenocarcinoma." (PMID 41350724, 2025). "Targeting PRKCSH may represent a promising therapeutic strategy to promote ferroptosis and anti-tumor immunity in lung adenocarcinoma." (PMID 41350724, 2025).
polycystic kidney disease (3 papers, 2015 to 2023). A usually autosomal dominant and less frequently autosomal recessive genetic disorder characterized by the presence of numerous cysts in the kidneys leading to end-stage renal failure. "Both these molecules are involved in autosomal dominant polycystic kidney and liver diseases, and PRKCSH acts as a chaperone-like molecule to regulate PKD2 expression." (PMID 25528770, 2015).
Renal cyst (3 papers, 2015 to 2025). A fluid filled sac in the kidney. "A small number of renal cysts is common in this population, which is atypical in PRKCSH- and SEC63-caused ADPLD." (PMID 37628703, 2023). "Patients harboring heterozygous germline mutations in PRKCSH are thought to develop renal cysts as a result of somatic loss of the second allele, which subsequently interferes with expression of the TRP channel polycystin-2 (PKD2)." (PMID 26671672, 2015).
glioma (2 papers, 2024). A benign or malignant brain and spinal cord tumor that arises from glial cells (astrocytes, oligodendrocytes, ependymal cells). "Similarly, another model for predicting the prognosis of lower-grade gliomas, which is based on four RNA-edited sites (PRKCSH chr19:11561032, DSEL chr18:65174489, UGGT1 chr2:128952084, and SOD2 chr6:160101723), also reported an AUC of 0.823." (PMID 39764127, 2024).